INS (insulin)
Diseases named in the same sentence as INS in open-access papers (continued):
Sharing a sentence is not in itself a finding about the gene and the disease.
Insulin resistance (continued). "Fasting hyperinsulinemia is associated with insulin resistance, but intravenous and oral glucose tolerance tests (IVGTT and OGTT) predict better insulin resistance in obese children despite having similar fasting serum insulin levels." (PMID 35586622, 2022). "In women with GDM, both impaired insulin secretion and insulin resistance was observed." (PMID 35207731, 2022). "In the AT, insulin acts as an anti-lipolytic hormone; thus, insulin resistance might have led to the further lipid mobilisation from AT in HBCS cows." (PMID 36042230, 2022). "And the potential mechanism underlying the findings may be explained by the strong ties between hepatic steatosis and insulin resistance, which can interfere with insulin signaling in brain mechanisms." (PMID 36275825, 2022). "However, consistent with a role of SHP2 in promoting cellular insulin resistance by inhibiting insulin-evoked PI3K signaling, high sugar exposure-induced insulin-resistant hepatocytes overexpress SHP2 and display reduced PI3K/AKT signaling." (PMID 36140242, 2022). "Insulin resistance is a common etiology for metabolic syndrome (MetS), represented by a cluster of abdominal obesity, hyperlipidemia, hyperglycemia, and hypertension, which are interrelated to the attenuation of insulin signaling." (PMID 35054379, 2022). "We hypothesized that women with greater arsenic exposure would have greater insulin resistance and lower insulin secretion." (PMID 35031057, 2022). "Moreover, IFNαR1−/− mice prevented DIO-induced insulin resistance by improving GTTs, ITTs, and pyruvate tolerance tests and reducing plasma fasting glucose and insulin levels." (PMID 36552805, 2022). "The discrepant findings between pioglitazone and other insulin sensitizers including metformin and rosiglitazone suggest that factors other than the improvement of insulin resistance might be responsible." (PMID 35585577, 2022). "T2DM is a chronic condition in which the body’s ability to use insulin decreases (insulin resistance), and over time, the ability of the pancreas’s beta cells to produce enough insulin to meet the demand declines, resulting in high blood glucose or hyperglycemia." (PMID 36221145, 2022). "These negative results indicated that the protection against insulin resistance seen in Waved 2 mice in response to the HFD was not due to deficient EGFR activity in the primary peripheral insulin sensitive cell tissues." (PMID 35948530, 2022). "This could be caused by the insulin-resistant phenotype of these mice, as decreased AKT phosphorylation was described during insulin resistance." (PMID 36422892, 2022). "It is well documented that up to 80% of women with PCOS have impaired insulin sensitivity, and as a consequence, insulin resistance and hyperinsulinemia, contributing to the maintenance of hyperandrogenemia and to the development of cardiometabolic diseases in those women." (PMID 36012206, 2022). "Since up-regulation of G6PD impaired insulin signaling response, we next explored whether high-fat treatment could result in insulin resistance by increasing G6PD." (PMID 35806430, 2022). "Insulin resistance could induce hyperinsulinemia due to the excess production of insulin by pancreatic β-cells." (PMID 36003786, 2022). "Improper functions of insulin and insulin resistance in tissues induced by hyperglycemia results mobilization of fatty acids in the tissues, simultaneously production of free radicals and decreased levelsof anti oxidants leads to many micro and macro vascular complications particularly on kidney." (PMID 37654826, 2022). "However, insulin resistance is defined as reduced insulin sensitivity and brain insulin resistance as a failure of neurons and glia to respond to insulin." (PMID 35765060, 2022). "Targeting the human equivalent to TLR13 or genes that suppress it may be a therapeutic modality in improving insulin signaling and preventing the profound catabolic consequences of insulin resistance in CKD." (PMID 35088922, 2022).
Insulin resistance (continued). "Long-term GH action inhibits insulin sensitivity and induces insulin resistance." (PMID 36686475, 2022). "Patients with diabetic kidney disease (DKD) undergoing hemodialysis develop insulin secretory defects along with insulin resistance, and their blood insulin levels may be reduced below normal." (PMID 36362467, 2022). "As calcium is essential for several insulin-mediated intracellular processes in muscle and adipose tissue, hence vitamin D may be related to its effect on insulin resistance." (PMID 35546181, 2022). "Flavonoids are also known to play an important role in decreasing hepatic inflammation, hepatic oxidative stress, and can boost insulin-mediated activities in the hepatic cells, skeletal cells, as well as in adipose tissue, all of which can help with insulin resistance." (PMID 35268685, 2022). "A ketogenic diet decreases intrahepatic insulin resistance and, thus, serum insulin concentration." (PMID 36615809, 2022). "Some studies have found that a high circulating selenium level is correlated with impaired insulin signaling and could potentially modulate liver insulin resistance, and insulin resistance plays a pivotal role in the development of hepatic lipid accumulation." (PMID 35267927, 2022). "Moreover, pro-inflammatory cytokines such as TNF-α and IL-6 interfere with the insulin signaling pathway and increase insulin resistance under stress conditions." (PMID 36079032, 2022). "In general, it can be said that lipid‐induced insulin resistance is predominantly mediated by DAGs, in addition to this lipid‐mediated mechanism also chronic tissue inflammation (e.g., cytokines and chemokines) can impair insulin signaling." (PMID 35830259, 2022). "Obesity has been correlated with insulin resistance and elevations in insulin levels." (PMID 36360622, 2022). "One reason is that avoiding chronic insulin spikes is important in preventing insulin resistance." (PMID 36364827, 2022). "Moreover, fetuin-A levels among obese diabetic patients correlated with obesity, higher daily insulin requirement, and insulin resistance." (PMID 36578961, 2022). "This raises the possibility that in Alb-R26Met mice, increased MET levels facilitate a MET-IR complex formation that might be partially signaling compromised, at least in response to insulin stimulation, resulting in insulin resistance." (PMID 35269415, 2022). "Enigmatically, although thyroid dysfunction has been traditionally associated with the notion of insulin resistance, our data unexpectedly showed no significant changes in insulin and HOMA-IR values when hyperthyroidism was corrected." (PMID 35894647, 2022). "However, the significance of insulin and insulin resistance reductions was partly driven by a worsening in the control arm." (PMID 35276815, 2022). "Therefore, attempts to overcome SIH consist of using agents such as insulin, metformin, vitamin D, and magnesium which are beneficial in reducing insulin resistance and inflammatory pathways." (PMID 35178208, 2022). "When high-fat diet and obesity will cause the increase in fatty acids in blood exceeding the oxidation capacity of skeletal muscle, excessive esterified fatty acids are deposited in skeletal muscle, which will affect insulin-mediated signal transduction and lead to insulin resistance." (PMID 35811955, 2022). "Different from type 1 DM and gestational diabetes, the major pathogenesis of type 2 DM is insulin resistance and beta-cell dysfunction accompanied with insufficient insulin secretion, where insulin resistance is generally defined as dysfunctional insulin-mediated glucose clearance." (PMID 35721855, 2022). "It is manifested by insulin resistance and disturbed insulin secretion." (PMID 35781592, 2022). "The elevated fasting insulin indicated possible insulin resistance in the STZ&HFD mice." (PMID 35260560, 2022).
Insulin resistance (continued). "The possible mechanism of insulin resistance in NAFLD is that increased hepatic insulin and impaired glucose are involved in hepatic de novo lipogenesis, which activate sterol regulatory element-binding protein 1c (SREBP-1c) and carbohydrate response element-binding protein (ChREBP), respectively." (PMID 36556179, 2022). "Targeting TLR13 may prove to be a therapeutic modality by improving insulin signaling and preventing the profound catabolic consequences of insulin resistance in CKD." (PMID 35088922, 2022). "They feature a marked metabolic activity and therefore rely on a vast amount of energy supplied by their mitochondria, especially when a supraphysiologically high level of insulin secretion is required to overcome insulin resistance and ameliorate hyperglycemia." (PMID 35453472, 2022). "We also assessed fasting blood glucose and insulin concentrations to determine whether HFD induces insulin resistance." (PMID 36142528, 2022). "The reduction in the RBC count may be explained by the effects of insulin resistance in prediabetes, where insulin has a role in regulating erythropoiesis." (PMID 35497944, 2022). "Hence, protein intake can contribute to alterations in insulin sensitivity and promote insulin resistance." (PMID 35267895, 2022). "Of these cases, approximately 90% are type 2 diabetes (T2D), where developed insulin resistance and increased insulin demand prevents glucose mobilization and provokes pancreatic β-cell dysfunction culminating in insufficient insulin quantities and hyperglycemia." (PMID 36030052, 2022). "Several studies have shown that chronic hyperinsulinemia lead to a state of selective insulin resistance, reducing signaling efficiency for certain insulin-signaling nodes while sparing others which could be responsible for inducing senescence." (PMID 35872305, 2022). "There were three main modeling methods of HepG2 cell insulin resistance model, high-glucose induced cell insulin resistance model, high-concentration insulin induced cell insulin resistance model, and fatty acid (palmitic acid) induced cell insulin resistance model." (PMID 35548575, 2022). "The generation of the massive pro-inflammatory cytokines further exacerbates the inflammatory reaction, which could potentiate insulin resistance by altering the insulin signaling pathways." (PMID 36438767, 2022). "Type-2 diabetes (T2D) is characterized by defective insulin secretion and/or insulin resistance." (PMID 35204134, 2022). "The primary defect leading to pregnancy hyperglycemia may be excess insulin resistance, inadequate insulin secretion, or both, and it seems that obstetric and perinatal outcomes vary to some extent between physiologic GDM subtypes." (PMID 36432486, 2022). "Insulin has anti-apoptotic activity, and insulin resistance is known to induce apoptosis." (PMID 36233134, 2022). "The sex difference has been explained by an early-phase insulin release and insulin resistance." (PMID 36432554, 2022). "Therefore, targeting factors and receptors related to skeletal muscle insulin action can help improve insulin resistance in type 2 diabetes to prevent further progression." (PMID 36235831, 2022). "Furthermore, the present authors have recently revealed that PPARG is the first gene abnormally expressed as a result of induction of insulin resistance, which proves its crucial role in the regulation of insulin sensitivity." (PMID 35684107, 2022). "This is due to the development of insulin resistance, which makes it difficult for insulin to work." (PMID 36558381, 2022). "Hyperinsulinemia may have elicited insulin resistance development through a mechanism of oxidative stress and may further impair the body’s insulin sensitivity response during exercise." (PMID 36083870, 2022).
Insulin resistance (continued). "Intestinal secretion of GRP78 may be the cause of insulin resistance, and duodenal jejunal bypass surgery may reduce GRP78 secretion and improve insulin sensitivity by shortening food transportation or reducing lipid stimulus released from endocrine cells." (PMID 36498048, 2022). "Impairment of insulin signaling leads to insulin resistance, which is a pathological condition, related to excess secretion of insulin as a compensation mechanism to maintain the stability of glucose level in the blood since a suitable response to increased glucose is not observed." (PMID 35807828, 2022). "So, the different indicators of insulin resistance/insulin sensitivity used in different studies may be the reason for the discrepancy in previous studies." (PMID 35299970, 2022). "Interestingly, by reducing the oxidative damage, silibinin improves insulin sensitivity, thus reducing the glycemia and insulinemia and improving the homeostatic model assessment for insulin resistance (HOMA) index." (PMID 35269912, 2022). "In addition to its known effect on the vascular function, ET-1 also limits insulin actions in skeletal muscles and adipocytes leading to insulin resistance and impaired glucose tolerance." (PMID 35681200, 2022). "Failure of insulin to induce a response in neuroimaging is considered a sign of insulin resistance." (PMID 36038539, 2022). "Since then, molecular studies have shed light on the relationship between T2DM and GDM, and have demonstrated important similarities between the pathophysiology of both disorders such as increased insulin resistance or a limited ability of the β-cell to overcome insulin insensitivity." (PMID 35408874, 2022). "In addition, high fasting serum insulin levels is another sign of insulin resistance, and GL was found to decrease fasting serum insulin levels in diabetic rodents." (PMID 36232291, 2022). "Moreover, the proinflammatory cytokines are also involved in promoting insulin resistance in insulin-sensitive organs, resulting in T2DM development." (PMID 35335211, 2022). "In group 4, insulin resistance was high, and insulin secretion function was low." (PMID 35672344, 2022). "In addition, the pancreas will try to compensate for insulin resistance by increased insulin production resulting in hyperinsulinemia." (PMID 35955975, 2022). "Furthermore, treating obese cells or animals with IL-1β has been observed to induce insulin resistance by inhibiting the insulin signaling pathway." (PMID 36364954, 2022). "The average degree of signaling pathway was 6.25, and 7 signaling pathways were higher than this value: AMPK signaling pathway, adipocytokine signaling pathway, pathways in cancer, insulin resistance, insulin signaling pathway, non-alcoholic fatty liver disease, PI3K-Akt signaling pathway." (PMID 36699034, 2022). "Long-term stress activates the hypothalamus-pituitary-adrenal axis, increasing the concentration of corticotropin-releasing hormones, which have been found to be increased in women with HDP, and cortisol, an insulin-antagonist that can contribute to insulin resistance." (PMID 34897523, 2022). "As a relevant example, Dapagliflozin was able to improve brain mitochondrial function and insulin signalling, thus preventing neuronal dysfunction and cognitive decline in obese insulin-resistant rats, with a marked reduction of insulin resistance and brain oxidative stress." (PMID 36293181, 2022). "This suggests that mechanisms other than Akt-mediated insulin signaling may be involved in insulin resistance induced by TCDD exposure." (PMID 36358481, 2022). "Conversely, it has been suggested that ANG II-induced insulin resistance may involve enhanced oxidative stress, which inhibits insulin signaling downstream from PI3-kinase activation." (PMID 36290746, 2022).
Insulin resistance (continued). "Serum insulin levels were also measured, and the homeostasis model assessment of insulin resistance (HOMA-IR) was 3.16 ± 0.72 (ranging from 2.44 to 3.89), which were also higher than the population-based reference interval of HOMA-IR in healthy lean cats (0.4~2.1)." (PMID 35467389, 2022). "Moreover, acupuncture regulates the phosphorylation of insulin substrates and receptors and inhibits the abnormal expression of signaling pathways, thereby improving metabolic dysfunction such as insulin resistance." (PMID 36353235, 2022). "In human studies, the presence of ENPP1 rs1044498*C polymorphism in Caucasian populations is associated with insulin resistance when assessed by the homeostasis model assessment (HOMA-IR), accompanied by elevated HbA1c, fasting insulin, and fasting plasma glucose levels." (PMID 35055468, 2022). "Insulin resistance (IR), defined as a condition with impaired insulin action and response in tissues, is widely considered to be one of the most fundamental factors associated with the development of many metabolic disorders, e.g., type 2 diabetes mellitus or metabolic syndrome." (PMID 35328503, 2022). "In this regard, blocking the inhibitory effect of PCTP/ACOT13 and leucine might enable insulin to suppress PPARa activity for longer and avoid insulin resistance." (PMID 35269927, 2022). "TNF-α develops insulin resistance, whereas adiponectin improves insulin sensitivity." (PMID 35010830, 2022). "Interestingly, while DEX increased plasma insulin concentrations and worsened insulin resistance in fasting and postprandial states (HOMA-IR index and ISI-M) compared to CON, the decrease in insulin sensitivity was partially revered by the EAA-enriched diet." (PMID 35050206, 2022). "Furthermore, elderly statin users demonstrated significantly worse glycemic control in serum insulin and homeostatic model assessment—insulin resistance (HOMA-IR) index." (PMID 35627914, 2022). "Insulin resistance (IR) is a condition in which the response of organs to insulin is impaired." (PMID 36224569, 2022). "Therefore, mice with NE deficiency or MPO deficiency have reduced adipose tissue inflammation and improved carbohydrate metabolism, including improved glucose tolerance and insulin sensitivity and a reduction in insulin resistance." (PMID 35039631, 2022). "The secondary outcome was dietary intake, anthropometric indices, serum insulin and Homeostatic Model Assessment of Insulin Resistance (HOMA-IR), total antioxidant capacity (TAC), tumor necrosis factor (TNF), high-sensitivity C-reactive protein (hs-CRP), malondialdehyde (MDA), and lipid profile." (PMID 35870947, 2022). "Insulin resistance develops in parallel to the impairment of renal function, while diminished renal insulin clearance may contribute to hyperinsulinemia; the kidney is responsible for 10–20% of insulin clearance from the systemic circulation." (PMID 35683611, 2022). "In 2006, a hypothesis was proposed that insulin secretion is affected by the social environment, but the data generated were severely confounded by increases in obesity and insulin resistance." (PMID 35947600, 2022). "The DNA methylation alternations in those genes might contribute to expression changes of these gene, which further aggravates insulin resistance and insulin secretion." (PMID 35606885, 2022). "Initially, β cells compensate for insulin resistance through upregulation of insulin secretion (β-cell adaptation), but over time they may be unable to meet the increased insulin demand and overt T2DM manifests." (PMID 36260620, 2022). "Our analyses further validated the positive association of DAS with insulin and HOMA‐IR (both p < 5 × 10−3), suggesting that baseline gut antibiotic resistome was associated with T2D progression, characterized by the alteration of insulin resistance." (PMID 35142450, 2022).